STAT3 (signal transducer and activator of transcription 3)
Diseases named in the same sentence as STAT3 in open-access papers (continued):
Sharing a sentence is not in itself a finding about the gene and the disease.
pancreatic cancer (continued). "Overall, these studies show that the simultaneous targeting of APE1 redox and STAT3 signaling synergize to markedly impair the survival of human pancreatic cancer cells, even at sub-optimal doses of the individual agents." (PMID 23094050, 2012). "STAT3 in particular, is constitutively active in a wide variety of human cancer cell lines and tissues, including breast and pancreatic cancer." (PMID 23056374, 2012). "In this paper, we examined the effects of EGCG on STAT3 signaling in human pancreatic cancer cells, and also assessed the interactive effects of EGCG with gemcitabine or JAK3 inhibitor CP690550 on their therapeutic potential." (PMID 22348037, 2012). "STAT3 is activated in cells within the ductal structures in human pancreatic cancer and in a mouse model of this cancer." (PMID 23077629, 2012). "In conclusion, we found that YM155, known as a survivin inhibitor, promotes downregulation of PI3K, p-ERK, and p-STAT3 through degradation of EGFR in pancreatic cancer cells." (PMID 22723871, 2012). "Overall, these results suggest that EGCG suppresses the growth, invasion and migration of pancreatic cancer cells, and induces apoptosis by interfering with the STAT3 signaling pathway." (PMID 22348037, 2012). "In the current study, we showed that knockdown of STAT3 expression decreased MMP-7 expression in pancreatic cancer cells and nude mouse xenografts." (PMID 21991388, 2011). "Taken together, our results suggest that BITC suppresses pancreatic tumor growth by inhibiting tumor angiogenesis through STAT-3-dependant pathway." (PMID 22016776, 2011). "Our previous studies have shown that benzyl isothiocyanate (BITC) suppresses pancreatic tumor growth by inhibiting STAT-3; however, the exact mechanism of tumor growth suppression was not clear." (PMID 22016776, 2011). "Recent work showed that the inflammatory mediator Stat3 is activated at all stages of pancreatic cancer from low-grade PanIN to PDAC and is required for cancer progression." (PMID 22140463, 2011). "In pancreatic cancer, activation of STAT-3 promoted tumor cell growth, invasion, and metastasis, leading to poor patient survival." (PMID 21991388, 2011). "To demonstrate the role of STAT3 in pancreatic cancer, we performed gene knockdown experiments using STAT3 shRNA in SW1990 cells." (PMID 21991388, 2011). "In pancreatic cancer, recent studies have demonstrated inappropriate and constitutive activation of STAT3." (PMID 21991388, 2011). "Previous data from our group suggests that knockdown of STAT3 inhibited invasion of pancreatic cancer SW1990 cells in vitro and markedly decreased VEGF and MMP-2 expression." (PMID 21991388, 2011). "Our previous studies have demonstrated that BITC suppresses pancreatic tumor growth by inhibiting STAT-3." (PMID 22016776, 2011). "In a previous study by our group, we reported down-regulation of STAT3 expression suppressed invasion capacity of pancreatic cancer cells in vitro." (PMID 21991388, 2011). "In ours study, we found that STAT3 inhibition can reduce MMP-7 expression in pancreatic cancer cells." (PMID 21991388, 2011). "Taken together, our data provides convincing evidence that BITC inhibits pancreatic tumor angiogenesis by targeting STAT-3 and inhibiting HIF-1α/VEGF/MMP-2/Rho-GTPases." (PMID 22016776, 2011). "We previously reported that Curcumin analogue GO-Y030 inhibits STAT3 activity and cell growth in breast and pancreatic carcinomas." (PMID 21694723, 2011). "Abnormal activation of Stat3 plays an important role in the invasion and metastasis of pancreatic cancer." (PMID 20482858, 2010). "To evaluate the effects of regulation of Stat3 activity on pancreatic cancer invasion, we performed an in vitro invasion assay using AG490 and IL-6." (PMID 20482858, 2010). "Our previous study also found that silencing of the Stat3 gene by RNAi decreases VEGF expression in the pancreatic cancer cell line SW1990." (PMID 20482858, 2010).
pancreatic cancer (continued). "Collectively, our findings strongly suggest that the Jak/Stat3 pathway plays a significant role in pancreatic cancer cell invasion." (PMID 20482858, 2010). "Previous studies have demonstrated that activated Stat3 is overexpressed in human pancreatic cancer tissues and cell lines." (PMID 20482858, 2010). "Abnormal activation of Stat3 plays a critical role in metastasis and invasion in varieties of human tumors including pancreatic cancer." (PMID 20482858, 2010). "This study aimed to investigate the mechanisms of activation and blocking of the Stat3 signaling pathway and its effects on invasion and metastasis of human pancreatic cancer cells." (PMID 20482858, 2010). "Recent studies of pancreatic cancer reported that ZIP4 activates the IL-6/Stat3 pathway via CREB, leading to increased expression of neuropilin-1, vascular endothelial growth factor, and matrix metalloproteases." (PMID 20957146, 2010). "We also examined the expression of Stat3 and its active phosphorylated form in human pancreatic cancer cell lines." (PMID 20482858, 2010). "All human pancreatic cancer cells tested expressed various levels of Stat1, Stat3, and Stat6 proteins." (PMID 15714203, 2005). "A very faint Stat3 band was also detectable in the other cell lines after a long exposure; Stat6 (120 kDa) was also expressed in pancreatic cancer cells at various levels, with the highest levels found in COLO-357 cells." (PMID 15714203, 2005). "Downregulation of SOCS-1 by gene promoter hypermethylation has been recently reported in 65% of HCC cell line, 62.9% of multiple myeloma patients samples and 31.6% of pancreatic cancer cell lines with resultant activation of STAT3." (PMID 15354212, 2004). "However, one mechanism is considered the main promoter of anoikis resistance in pancreatic cancer: over-expression and activation of the transcription factor STAT3." (PMID 41596231, 2026). "In addition, the transformation of monocytes to M-MDSCs was dependent on STAT3 activation contributing to stemness and increased mesenchymal properties in pancreatic cancer." (PMID 40427186, 2025). "In addition, knockdown of STAT3 expression in pancreatic cancer cells significantly inhibited cell invasion and MMP‐7 expression." (PMID 41425852, 2025). "Furthermore, in pancreatic cancer, PKCζ phosphorylates signal transducer and activator of transcription 3 (STAT3) at Tyr705, leading to its activation." (PMID 41244006, 2025). "In non-neuronal systems, cathepsin-B expression is regulated by signal transducer and activator of transcription 3 (STAT3); the ferroptosis inducer erastin has been shown to cause lysosomal dysfunction and cathepsin-B upregulation via aberrant STAT3 activation in pancreatic cancer cells." (PMID 41304754, 2025). "In conclusion, MCPIP1 inhibited the IL6/JAK/STAT3 axis in pancreatic tumors." (PMID 40874680, 2025). "Finally, to further explore and verify that CTHRC1 in CAFs activates the STAT3 signaling pathway in pancreatic cancer cells by regulating LIF, we cocultured CAFs‐CM with pancreatic cancer cells and added the LIF inhibitor EC330 at various concentrations." (PMID 40751418, 2025). "The authors of the study also investigated the utility of this combination treatment in vivo using an orthotopic animal model and found that it significantly inhibited pancreatic cancer growth, delayed tumor quadrupling times, and inhibited autophagy and STAT3 in pancreatic tumors." (PMID 40227400, 2025). "N4 targets the STAT3 SH2 domain in pancreatic cancer and selectively blocks pY705 over pS727." (PMID 40075607, 2025). "Additionally, YY002, another dual-phosphorylation synchronous inhibitor, effectively suppresses pancreatic cancer growth and metastasis in preclinical models, exhibiting superior therapeutic efficacy compared with the clinical-stage STAT3 inhibitor BBI608." (PMID 41463025, 2025).
pancreatic cancer (continued). "Additionally, pancreatic cancer-derived exosomal miRNA let-7b-5p activates STAT3/FOXO1 signaling, exacerbating insulin resistance and muscle wasting." (PMID 40704145, 2025). "Investigating how STAT3 regulates β3 expression in pancreatic cancer cells revealed a striking dichotomy, since only certain cell lines lacking endogenous β3 expression could upregulate its expression." (PMID 40701148, 2025). "It accomplished anti-pancreatic cancer effect by inhibiting Stat3 signaling." (PMID 40894227, 2025). "Accordingly, we identified genes upregulated by STAT3 in pancreatic cancer cells exposed to hypoxia and inflammatory cytokines, reasoning that their intersection would represent a fundamental role for STAT3 in adapting to the effects of cellular stress or inflammatory signals." (PMID 40701148, 2025). "These insights suggest that targeting the IL-6/GP130/JAK/STAT3 axis may offer a promising therapeutic strategy for pancreatic cancer." (PMID 41397158, 2025). "Targeting the NF-κB/STAT3 pathway could therefore provide a potential strategy to overcome chemoresistance in pancreatic cancer treatment." (PMID 39796244, 2025). "Additionally, blocking STAT3 effectively treats perineural invasion of pancreatic cancer cells in vivo." (PMID 40940782, 2025). "Wörmann observed more potent maintenance of STAT3 activation by ROS in pancreatic cancer tissue." (PMID 39877839, 2025). "Specifically, we observed elevated levels of MAPK (p-ERK-T202-Y204), Vimentin, YAP (pS127), AMPK (pT172), eIF4G, Myosin-IIa (pS1943), Stat3 (pY705) and B-Raf (pS445), suggesting that M2 macrophage-derived exosomes induce various oncogenic signaling pathways in pancreatic cancer cells." (PMID 40624025, 2025). "Moreover, LIF is the most important molecule in activating the STAT3 signaling pathway in pancreatic cancer." (PMID 40751418, 2025). "The results showed that activated CAFs significantly promoted the phosphorylation of STAT3 in pancreatic cancer cells and induced activation of the STAT3 signaling pathway, suggesting that this may be related to the high expression of CTHRC1 in CAFs." (PMID 40751418, 2025). "Moreover, EVO also suppresses autophagy by inhibiting the phosphorylation of signal transducer and activator of transcription 3 (STAT3) in pancreatic cancer cells." (PMID 41209568, 2025). "Thus, genetic silencing of STAT3 or pharmacological inhibition of its upstream kinases prevents pancreatic cancer cells from gaining integrin β3 expression in response to cytokines or stress in vitro." (PMID 40701148, 2025). "However, the prevalence and clinical relevance of IL-6/GP130/JAK/STAT3 pathway activation in patients with pancreatic cancer remain poorly defined." (PMID 41397158, 2025). "Targeting STAT3 with inhibitors offers a promising strategy to overcome therapeutic resistance and curb metastatic spread, presenting an exciting avenue for precision therapy in pancreatic cancer." (PMID 39199647, 2024). "STAT3 expression in pancreatic cancer cells activates VEGF expression, promoting angiogenesis." (PMID 39195299, 2024). "This briefly illustrates the broad impact of STAT3 in pancreatic cancer." (PMID 38464736, 2024). "This may suggest that STAT3 plays a promoting role in pancreatic cancer progression, perhaps in part by inducing overexpression of ZDHHC20." (PMID 38821916, 2024). "Furthermore, using xenograft cancer models in vivo indicated that inhibiting STAT3 with panaxadiol limited the progression of pancreatic cancer." (PMID 38464736, 2024). "Moreover, knockdown or inhibition of STAT3 significantly reduced ZDHHC20 expression, overexpression of STAT3 resulted in significantly upregulation of ZDHHC20 in pancreatic cancer cells." (PMID 38821916, 2024). "Furthermore, CuI-induced suppression of pancreatic cancer cell growth appears to include JAK2/STAT3 signaling pathway suppression because JAK2/STAT3 activators successfully prevented the inhibition." (PMID 38397437, 2024).
pancreatic cancer (continued). "Additionally, through JAK2/STAT3 downregulation, CuB reduced the size of pancreatic cancer xenografts in athymic nude mice compared to controls without apparent drug toxicities." (PMID 38397437, 2024). "Our results demonstrate that XYA-2 inhibits STAT3 phosphorylation in pancreatic cancer cells." (PMID 38250721, 2024). "Taken together, thiswork not only revealed a novel STAT3 Tyr705 and Ser727 phosphorylationinhibitor as a promising new therapeutic agent for pancreatic cancer,but also provided insights into approaches to the development of STAT3Tyr705 and Ser727 phosphorylation inhibitors." (PMID 38559310, 2024). "On the other hand, tumors treated with gemcitabine alone displayed an increase in STAT3 levels; this effect has been observed in other studies and is suggested to be a potential contributor to gemcitabine resistance in pancreatic cancer cells." (PMID 39200368, 2024). "In addition, bioinformatic analysis showed a positive correlation between ZDHHC20 and STAT3 mRNA levels in various cancers, including pancreatic cancer." (PMID 38821916, 2024). "This suggests that XYA-2 may, at least in part, exert its anti-cancer effects through the modulation of apoptosis-related proteins and the inhibition of STAT3 phosphorylation in pancreatic cancer cells." (PMID 38250721, 2024). "Moreover, gemcitabine treatment can induce activation of NfkB and STAT3 in pancreatic cancer and can thereby induce resistance to itself." (PMID 37719017, 2023). "We observed that NT5E expression was associated with several gene sets linked to amoeboid migration and pancreatic cancer progression, such as transforming growth factor–β (TGF-β), KRAS, WNT, nuclear factor κB (NF-κB) and IL-6/JAK/STAT3 signaling, hypoxia, or EMT." (PMID 37851808, 2023). "In addition, the anti-CD147 drug metuximab sensitizes pancreatic cancer cells to chemoradiotherapy by reducing the CSC subpopulation via blockade of CD44/STAT3 signaling." (PMID 36902161, 2023). "Moreover, overexpression of PTRH1 reversed PD-L1 protein expression in pancreatic tumor cells when cultured in 25 mM sugar medium under the combined inhibition of STAT3 and PI3K phosphorylation." (PMID 37434177, 2023). "In pancreatic cancer models, STAT3 activation in CAFs promotes an immunosuppressive phenotype." (PMID 37199043, 2023). "Notably, treating pancreatic cancer cells with Stattic, a STAT3 inhibitor, substantially reversed the upregulation of mRNA expression of tumor stemness markers (NANOG, SOX2 and POU5F1) induced by IL20RB overexpression." (PMID 38098005, 2023). "In addition, CD147 promotes pancreatic cancer cell invasion by upregulating the EGFR/STAT3 signaling pathway." (PMID 37298389, 2023). "STAT3 inhibitor, which exhibits synergy in the suppression of pancreatic cancer growth." (PMID 36975494, 2023). "This suggests that CD73 may be one of the proteins that inhibits STAT3 activity in pancreatic cancer." (PMID 37835536, 2023). "In addition, the combination of PFTS and phospho-valproic acid, a new STAT3 (signal transducer and activator of transcription 3) inhibitor, has been shown to exhibit synergistic effects in pancreatic cancer." (PMID 36975494, 2023). "Another upregulated miRNA, miR-155, could also downregulate the expression of the suppressor of cytokine signaling (SOCS1) to increase the phosphorylation of STAT3 and promote the proliferation and invasion of pancreatic cancer cells." (PMID 38139352, 2023). "Our previous study on tissue micro-arrays from a cohort of 175 patients with PDAC showed that STAT3, phosphorylated STAT3, and IL-6 were expressed in more than half of the examined pancreatic tumors, supporting the importance of this pathway in pancreatic cancer." (PMID 36495330, 2023). "Indeed, TAMs depletion by neutralizing CSF1R improves chemotherapeutic response through decreasing the STAT3 activation in pancreatic cancer stem cells." (PMID 35658848, 2022).
pancreatic cancer (continued). "For example, IL6 could promote the development and proliferation of pancreatic cancer cells through the STAT3–Pim kinase axis." (PMID 35401700, 2022). "As an active compound in green tea, gallocatechin gallate (EGCG) has antioxidant and anti-inflammatory properties and inhibits the activity of STAT3, which can inhibit the growth and migration of pancreatic cancer cells by interfering with the STAT3 signaling pathway." (PMID 36686745, 2022). "Gene expression profile analysis and further experiments showed that circFARP1 conferred GEM resistance by enhancing LIF expression and secretion in CAFs, thereafter increasing the expression of ABCC2, CDA and SOX2 by activating the STAT3 signaling pathway in pancreatic cancer cells." (PMID 35045883, 2022). "It is reported that the inhibition of JAK2/STAT3 phosphorylation enhanced the apoptosis mechanism in PDACs, suggesting that it may be a critical action point in pancreatic cancer." (PMID 36500220, 2022). "Furthermore, we showed that FBP1 bound to STAT3 and prevented STAT3 phosphorylation, which modulated the immune response and PD‐L1 antibody blockade efficiency in pancreatic cancer cells." (PMID 34854226, 2022). "STAT3 can be considered as the intersection of multiple oncogenic signaling pathways, activated in immune cells and cancer cells in pancreatic cancer TME, promoting the production of immunosuppressive factors that alter gene expression programs and suppress anti-tumor immune responses." (PMID 36291659, 2022). "In the future, it will be necessary to verify whether inhibition of the gp130/STAT3 pathway is effective for the attenuation of metastasis or the prevention of recurrence in pancreatic cancer through in vivo experiments targeting gp130." (PMID 35565185, 2022). "Erlotinib may become a stable targeted therapeutic drug for pancreatic cancer in the future due to its role in the EGFR/STAT3 pathway." (PMID 36291659, 2022). "In addition, the combination treatment of AZD-1950 (an antisense-STAT3 based drug) and durvalumab currently enters the phase II of the clinical trials for pancreatic cancer patients (NCT02983578)." (PMID 36173644, 2022). "Therefore, STAT3 plays a role in pancreatic cancer and its TME, leading to tumor-induced immunosuppression." (PMID 36291659, 2022). "The discovery and study of this novel anti-cancer drug that directly targets STAT3 may offer potential clinical benefits for the treatment of pancreatic cancer." (PMID 36291659, 2022). "Moreover, the CAF-stimulated monocytes are capable of inducing Stat3 and Akt phosphorylation in pancreatic cancer cells and subsequently increasing their growth." (PMID 35453676, 2022). "Acupuncture affecting pancreatic cancer through TLR4/NF-κB/IL-6/STAT3 pathway may be a potential method for the treatment of pancreatic cancer." (PMID 36105933, 2022). "Notably, Stat3 activation was markedly downregulated in pancreatic cancer cells treated with the supernatant from PSCs in conditions of miR-301a inhibition." (PMID 35211358, 2022). "Similarly, STAT3 overexpression partially rescued the TST-induced decrease in pancreatic cancer cell clonogenesis." (PMID 35859150, 2022). "the activated IL-6/STAT3 pathway upregulated autophagy levels in pancreatic cancer cells." (PMID 35559037, 2022). "Furthermore, brusatol can induce cell apoptosis and inhibit cell growth in pancreatic cancer through JNK/p38/MAPK/NF-κb/Stat3/Bcl-2 signaling pathway." (PMID 35370639, 2022). "The upregulation of STAT3 in pancreatic cancer may also depend on the expression and function of other genes." (PMID 36291659, 2022).